CLDN4 (claudin 4)
Description:
Can associate with other claudins to regulate tight junction structural and functional strand dynamics. May coassemble with CLDN8 into tight junction strands containing anion-selective channels that convey paracellular chloride permeability in renal collecting ducts (By similarity). May integrate into CLDN3 strands to modulate localized tight junction barrier properties. May disrupt strand assembly of channel-forming CLDN2 and CLDN15 and inhibit cation conductance. Cannot form tight junction strands on its own.
Synonyms: CPE-R; CPER; CPETR1; WBSCR8; hCPE-R; CPETR
Tractability: Small molecule: a structure with a bound ligand is known. Antibody: UniProt places it where antibodies can reach, with high confidence; its Gene Ontology location is reachable by antibodies, with high confidence; UniProt predicts a signal peptide or a membrane-spanning region; the Human Protein Atlas places it where antibodies can reach.
Gene: Protein-coding gene on chromosome 7 (73,799,542 to 73,832,690, forward strand). Ensembl gene ENSG00000189143.
Subcellular location: Cell junction, tight junction; Cell membrane
Subcellular location (Human Protein Atlas): Plasma membrane
Pathways (Reactome):
Cell-Cell communication: Tight junction interactions
Gene Ontology:
Molecular function: protein binding; identical protein binding; transmembrane signaling receptor activity; structural molecule activity
Biological process: establishment of skin barrier; positive regulation of cell migration; positive regulation of wound healing; regulation of cell morphogenesis; calcium-independent cell-cell adhesion; paracellular transport; renal absorption; circadian rhythm; female pregnancy; response to progesterone
Cellular component: bicellular tight junction; cell-cell junction; plasma membrane; tight junction; apical plasma membrane; apicolateral plasma membrane; basal plasma membrane; lateral plasma membrane; membrane
Genetic constraint (gnomAD): Loss-of-function variants: 12 observed, 13.49 expected, observed/expected ratio (o/e) 0.89, 90% interval 0.57 to 1.44. The upper end of that interval is the gene's LOEUF score, 1.44, which puts it in group 5 of 6, group 1 being the genes least tolerant of losing a copy. Missense variants: 252 observed, 306.51 expected, observed/expected ratio (o/e) 0.82, 90% interval 0.74 to 0.91. Synonymous variants: 152 observed, 144.95 expected, observed/expected ratio (o/e) 1.05, 90% interval 0.92 to 1.2.
Homologues: Orthologues: chimpanzee CLDN4 (100% identical), macaque CLDN4 (99% identical), rabbit CLDN4 (92% identical), pig CLDN4 (91% identical), dog CLDN4 (89% identical), guinea pig CLDN4 (88% identical), rat Cldn4 (84% identical), tropical clawed frog cldn4 (77% identical), mouse Cldn13 (37% identical). Paralogues in human: CLDN3 (69% identical), CLDN6 (63% identical), CLDN9 (63% identical), CLDN5 (49% identical), CLDN1 (46% identical), CLDN14 (45% identical), CLDN17 (45% identical), CLDN8 (44% identical), CLDN7 (44% identical), CLDN19 (43% identical), CLDN2 (40% identical), CLDN15 (38% identical), and 10 more.
Diseases named in the same sentence as CLDN4 in open-access papers:
CLDN4 is named in the same sentence as 224 diseases in open-access papers, as found by Europe PMC text mining. Sharing a sentence is not in itself a finding about the gene and the disease. The quoted sentences say what the papers report.
ovarian carcinoma (91 papers, 2005 to 2025). A malignant neoplasm originating from the surface ovarian epithelium. "In ovarian cancer tumors, claudin-4 is frequently upregulated and closely associated with genome instability and worse patient outcomes." (PMID 38867360, 2024). "Claudin 4 which is overexpressed in ovarian cancer and associated with poor survival was detected in the exosomes from 32 of 63 (50.8%) ovarian cancer patients but in only 1 of 50 (2%) healthy individuals." (PMID 38796525, 2024). "In ovarian cancer, CLDN4 overexpression was associated with a dampened PARP-inhibitor-mediated antiproliferation response, while inhibition of CLDN4 sensitized the tumor sections to it." (PMID 38731853, 2024). "The association of CLDN4 overexpression with carcinogenesis has also been suggested in pancreatic and ovarian cancers." (PMID 35742959, 2022). "EPCAM and Claudin 4 maintain the bicellular tight junction and their alteration is well implicated in ovarian cancer." (PMID 33663405, 2021). "Overexpression of CLDN4 occurs in a variety of epithelial and solid tumors, including pancreatic and ovarian cancers, and CLDN4 expression is also associated with more malignant phenotypes." (PMID 29856790, 2018). "Several lines of evidence support the association of high CLDN4 expression with chemoresistance in ovarian cancer." (PMID 28545541, 2017). "Our group also have recently demonstrated that the CPGs CLDN3 and CLDN4 are overexpressed in ovarian cancer in association with decreases in repressive histone marks." (PMID 24551595, 2014). "Consistent with this study, several lines of evidence support the association of high claudin-4 expression with chemoresistance of ovarian cancer." (PMID 24009024, 2013). "A number of protein-coding genes are overexpressed in ovarian cancer because of loss of DNA methylation, including maspin, claudin-3 and claudin-4." (PMID 21694727, 2011). "Using high-throughput technologies to analyze genetic fingerprints of ovarian cancer, we have discovered extremely high expression of the genes encoding the proteins claudin-3 and claudin-4." (PMID 20598131, 2010). "However, the molecular mechanisms underlying claudin-4 overexpression in epithelial ovarian cancer remain poorly understood." (PMID 39625235, 2025). "In cisplatin-resistant ovarian cancer cells, claudin-4 was overexpressed 7.2-fold and was one of the most overexpressed proteins, suggesting that it may be associated with cisplatin resistance in ovarian cancer." (PMID 35747825, 2022). "In addition to Nectin-4, other cell adhesion molecules, such as cadherins and claudin-4 have been implicated in spheroid formation and metastasis in ovarian cancer." (PMID 32629816, 2020). "Previous studies have shown that claudin-4 is associated with prognosis in breast or bladder cancer, and plays a role in breast cancer cell invasiveness and metastatic potential in addition to inducing angiogenic factors in ovarian cancer." (PMID 25871476, 2015). "Of note, claudin-4 was overexpressed by 7.2-fold in cisplatin-resistant cells and was one of the most overexpressed proteins, suggesting its possible association with cisplatin resistance in ovarian cancer." (PMID 24009024, 2013). "In addition to DNA methylation, our group reported that loss of repressive histone methylations, including H3K27me3 and H4K20me3, is also associated with the overexpression of claudin-3 and claudin-4 in ovarian cancer and claudin-4 in gastric cancer." (PMID 24009024, 2013). "In this study, we sought to determine whether the expression of claudin 4 is associated with outcome in ovarian cancer patients and may be involved in tumor progression." (PMID 21541062, 2011). "Furthermore, the claudin-4/SLC1A5/LAT1 axis was linked to the transport of amino acids across the plasma membrane as one of the potential cellular processes that significantly decreased survival in ovarian cancer patients." (PMID 38867360, 2024).
ovarian carcinoma (continued). "We hypothesized that loss of CLDN3 or CLDN4 activates an EMT in ovarian cancer cells." (PMID 23805314, 2013). "Further work in the area of chemo-resistant ovarian cancer has demonstrated that CD44+ ovarian cancer stem cells represent a small proportion of cancer cells capable of sustaining tumor growth and chemo-resistance and these cancer stem cells highly express genes encoding claudin-4." (PMID 23685873, 2013). "In ovarian cancer, Claudin-4 is frequently mislocalized outside tight junctions, where it participates in aberrant signaling pathways that promote tumor progression and metastasis." (PMID 41464164, 2025). "The study shows that serum-derived exosome Claudin 4 steadily increased with the advancement of cancer in patients with ovarian cancer." (PMID 40612948, 2025). "Our findings show that claudin-4 supports ovarian cancer cell survival by stabilizing the genome through nuclear and cell-cycle remodeling." (PMID 39625235, 2025). "To gain insights into claudin-4’s functional effects in ovarian cancer, we selected various EOC cells (OVCAR8, OVCA429, and OVCAR3)." (PMID 39625235, 2025). "This integrated approach bridges experimental findings with clinical applicability and underscores the translational importance of Claudin-4 in ovarian cancer." (PMID 41464164, 2025). "In epithelial ovarian cancer, overexpression of claudin-4 significantly contributes to therapy resistance through mechanisms associated with genomic instability regulation." (PMID 39625235, 2025). "Preclinical studies have also yielded antibodies against CLDN4 (to deliver toxins to pancreatic and ovarian cancer cells) and CLDN3." (PMID 40687428, 2025). "Clinically, in ovarian cancer patients, CLDN4 expression is higher in tumors from chemotherapy-resistant cases, and silencing CLDN4 in cell models increased cisplatin sensitivity." (PMID 40687428, 2025). "Compared with chemotherapy-sensitive patients, the expression of CLDN4 is higher in ovarian cancer tissues from chemotherapy-resistant patients." (PMID 40687428, 2025). "This study found that claudin-4 protects ovarian cancer cells by remodeling nuclear structure and slowing cell-cycle progression." (PMID 39625235, 2025). "Overall, these results suggest that targeting claudin-4’s functional effects through CMP and FSK reduces EOC cell survival during olaparib treatment, highlighting claudin-4’s potential to decrease olaparib resistance and promote ovarian cancer cell death." (PMID 39625235, 2025). "This provides proof-of-concept that CLDN3 and CLDN4 are not only markers of ovarian cancer, but also potential therapeutic targets for refractory disease." (PMID 40687428, 2025). "CLDN4 has been shown to alter expression patterns in various types of cancer, including gastric, pancreatic, and ovarian cancer." (PMID 38818040, 2024). "CLDN3 and CLDN4 also regulate cisplatin sensitivity in ovarian cancer cells via copper transporter (CTR1), while CLDN7 enhances cisplatin sensitivity in lung cancer cells via the caspase pathway." (PMID 38731853, 2024). "Thus, our results suggest a link between the association of claudin-4 with genomic instability and autophagy, with the transport of amino acids potentially acting as a regulator of autophagy and thereby impacting the clinical significance of claudin-4 in ovarian cancer." (PMID 38867360, 2024). "Nevertheless, despite the well-recognized clinical significance of claudin-4 in ovarian cancer, the molecular mechanisms by which it promotes the development of therapy resistance, as well as its association with genomic instability, remain poorly understood." (PMID 38867360, 2024). "The overexpression of CLDN4 has been reported in various cancers, including gastric cancer, pancreatic cancer, colorectal cancer, breast cancer, oral squamous cell carcinoma, ovarian cancer, bladder cancer, cholangiocarcinoma, and NSCLC." (PMID 38629624, 2024).
ovarian carcinoma (continued). "In ovarian cancer, loss of repressive histone methylations, including H3K27me3 and H4K20me3, is associated with increased expression of CLDN3 and CLDN4." (PMID 38731853, 2024). "CLDN4 overexpression has been detected in several cancers, including lung, gastric, colorectal, endometrial, uterine cervical, and ovarian epithelial cancers." (PMID 36982569, 2023). "In ovarian cancer cells, CLDN3 and CLDN4 loss of expression promotes epithelial-mesenchymal transition (EMT), suggesting a central role in epithelial phenotype." (PMID 36614243, 2023). "Claudin-4 is an integral constituent of tight junctions and is overexpressed in pancreatic cancer and ovarian cancer." (PMID 35401695, 2022). "c-CPE binding, which correlated with the expression of Claudin-4, aids the cytotoxic actions of carboplatin and paclitaxel by sensitizing epithelial ovarian cancer cells." (PMID 36077843, 2022). "On the other hand, ELFN1-AS1 was shown to exhibit an increased level in ovarian cancer, and its overexpression accelerated cell proliferation and migration through the modulation of miRNA-497-3p/CLDN4." (PMID 35251374, 2022). "Clinical trials are required to validate the promising results of the in vitro and in vivo studies for CLDN3 and CLDN4, possibly adding onto current ovarian cancer management." (PMID 35665865, 2022). "In contrast, hypermethylation of the CLDN4 gene and overexpression of CLDN4 have been reported in ovarian cancer." (PMID 35742959, 2022). "CLDN3 and CLDN4 is overexpressed in ovarian cancer and increases cell invasion and motility, thereby promoting tumor occurrence and metastasis (Agarwal, D'Souza, and Morin 2005)." (PMID 34721537, 2021). "In accord with these findings in ovarian carcinoma, Cldn4 expression has been reported to be reduced in the majority of gastric cancers and lower expression levels correlate with poorly-differentiated gastric adenocarcinomas." (PMID 35006480, 2021). "Studies have shown that claudin-4 (CLDN4) is highly expressed in ovarian cancer, gastric cancer, breast cancer, and hepatocellular carcinoma." (PMID 34887379, 2021). "Similar to our findings in prostate cancer, higher levels of Cldn3 and Cldn4 expression have been observed in aggressive ovarian cancers, than in normal ovarian cells." (PMID 35006480, 2021). "So far, CPE and C-CPE have been reported to cause intracellular translocation of the cytoplasmic membrane CLDN4 in colon and ovarian cancer cells." (PMID 32481659, 2020). "Consistently, overexpression of CLDN4 enhanced EMT in the ovarian cancer cells via a pathway involving PI3K/Akt and EMT transcription factor Twist118." (PMID 32269215, 2020). "Taken together, ovarian cancer frequently expresses a complex of EpCAM, claudin-4 or −7 and CD82 that is located in TEMs." (PMID 32091301, 2020). "Several genes silenced by promoter DNA hypermethylation such as MLH1, SULF1, SFRP, TNFRSF10A, UCHL1, and CLDN4 are related to platinum resistance in ovarian cancer." (PMID 33680048, 2020). "For example, overexpression of claudin-4 suggested shorter 5-year progression-free survival and overall survival of ovarian cancer, while low expression of claudin-4 indicated a shorter disease-free survival of breast carcinoma in situ." (PMID 33282635, 2020). "Clinically, a copy number abnormality was reported in 20% of the patients with ovarian cancer including claudin 4 (CLDN4), RAS oncogene family (RAB25), and ATP binding cassette subfamily F member 2 (ABCF2)." (PMID 33076944, 2020). "In this study, we report the identification of the EpCAM-claudin-4 or −7-CD82 complex in the ovarian cancer progression and metastasis in vitro." (PMID 32091301, 2020). "In a similar manner with our results, claudin-3 and claudin-4 upregulated in 90% of the ovarian cancer cells." (PMID 32091301, 2020). "Sp1 is a transcriptional factor known to regulate claudin-3 and claudin-4 promoter activity in ovarian cancer." (PMID 31861759, 2019).
ovarian carcinoma (continued). "It has been reported that the functions of CLDN4 and CGN are associated with tight junctions, while PVRL4 promotes cell–cell adhesion in ovarian cancer cells." (PMID 31372511, 2019). "Human claudin-4 has been well studied due to over expression in ovarian cancer, and the gene’s normal function is important for ovarian follicular development." (PMID 30770720, 2019). "The carcinomas in SCID pigs were morphologically similar to the original ovarian carcinoma and had the same immunohistochemical phenotype based on expression of Claudin 3, Claudin 4, Cytokeratin 7, p16, and EMA." (PMID 30723704, 2019). "Adding to this, knockdown of claudin-3 or claudin-4 in ovarian cancer cells induced resistance to cisplatin by the regulation of Cu transporter CTR1." (PMID 31861759, 2019). "Another study by a Japanese group of researchers reported a high expression of claudin-4 in the ovarian cancer tissues of platinum-resistant patients." (PMID 31861759, 2019). "Claudin-1 promotes EMT in human liver cells, while claudin-3 and claudin-4 promote EMT in ovarian cancer cells, which suggests that the effect of claudins on EMT is tissue-specific." (PMID 30728783, 2018). "Studies have shown that the effects of claudin-3 and claudin-4 are more pronounced in ovarian cancer cells." (PMID 30728783, 2018). "Further, the role of claudin-4 in pro-angiogenic and enhanced motility in ovarian cancer was also demonstrated." (PMID 30728783, 2018). "Ovarian cancer cells expressing CLDN4 show increased invasion, motility, and anti-apoptotic survival, and CLDN4 overexpression has been observed in advanced ovarian cancer." (PMID 30647838, 2018). "Expression of CLDN4 is upregulated in several types of epithelial malignancies, including pancreatic, urinary bladder and ovarian cancer." (PMID 30647838, 2018). "The levels of CLDN3 and CLDN4 were frequently elevated in pancreatic adenocarcinoma, ovarian cancer, endometrioid adenocarcinoma, and prostate cancer, while CLDN7 has been found to be decreased in invasive ductal carcinomas of the breast." (PMID 28867761, 2017). "In epithelial ovarian cancer, it has been demonstrated that claudin-4 is highly expressed by tumors of all subtypes, grades, and stages." (PMID 27724921, 2016). "In a mouse xenograft model of ovarian cancer we found that disruption of claudin-4 with DFYNP can significantly decreases tumor burden." (PMID 27724921, 2016). "To answer this question we used an established mouse xenograft model of ovarian cancer to examine the contribution of claudin-4 to overall ovarian tumor burden." (PMID 27724921, 2016). "Together these observations suggest that claudin-4 plays a critical role in promoting tumor cell survival and tumor spread, two major contributing factors to poor survival outcomes of ovarian cancer patients." (PMID 27724921, 2016). "Claudin-3 and claudin-4 control tumor growth and metastases through their regulation of β-catenin signaling in ovarian cancer xenografts." (PMID 26083392, 2015). "CLDN3 and CLDN4, which are separated by only 60 kb on chromosome 7, are transcribed in opposite directions and highly overexpressed in ovarian cancer." (PMID 24551595, 2014). "Because of their consistent overexpression in ovarian cancer, claudin-3 and claudin-4 have been suggested as potentially useful biomarkers for the detection and diagnosis of ovarian cancer." (PMID 24009024, 2013). "The C-CPE is also able to sensitize epithelial ovarian cancer cells to the cytotoxic effects of Taxol and Carboplatin at relatively low doses in a claudin-4 dependent manner." (PMID 23685873, 2013). "Because of the frequent dysregulation of claudin-3 and claudin-4 in ovarian cancer cells, the role of these claudins has mainly been reported in ovarian cancer." (PMID 24009024, 2013). "Increased claudin-4 levels have been shown in prostate cancer, ovarian carcinoma and in several other tumor cell lines." (PMID 23599806, 2013).